YY1 (YY1 transcription factor)
Diseases named in the same sentence as YY1 in open-access papers (continued):
Sharing a sentence is not in itself a finding about the gene and the disease.
lymphoma (11 papers, 2016 to 2023). A malignant (clonal) proliferation of B- lymphocytes or T- lymphocytes which involves the lymph nodes, bone marrow and/or extranodal sites. "Based on independent findings regarding the expression of HIF-1α and YY1 in lymphomas and leukemia, we proposed that there is a correlation between these proteins." (PMID 35163649, 2022). "Recent studies have demonstrated the constitutive expression of YY1 in lymphoma, and its expression correlates with some subtypes of more aggressive lymphomas." (PMID 31040909, 2019). "Based on independent findings regarding the expression of KLF4 and YY1 in lymphomas, we proposed that there is a correlation between these proteins." (PMID 31040909, 2019). "Likewise, our working group and other groups have reported that the transcription factor YY1 is expressed in high levels in lymphomas, and we recently reported that this transcription factor regulates the expression of KLF4 in lymphoma cell lines." (PMID 33194748, 2020). "Interestingly, we found a positive correlation between the expression of KLF4 and YY1 in several data sets analyzed from the lymphoma study by Campagno." (PMID 31040909, 2019). "In addition, the transcription factor YY1 is expressed in lymphomas, and computational analysis has shown that its expression correlates with poor survival in lymphoma patients." (PMID 31040909, 2019). "We analyzed the expression of KLF4 and YY1 for each subtype of lymphoma included in the TMA." (PMID 31040909, 2019). "However, whether the regulatory role of YY1 in lymphoma is suitable for the regulation of tumor by B cells in the tumor microenvironment needs to be further confirmed in future studies." (PMID 37081988, 2023). "We also propose that the use of pharmacological or chemical inhibitors targeting YY1 and KLF4 could be an alternative treatment for patients with lymphoma that are known to be positive for YY1 and KLF4 expression, thus offering a therapeutic alternative for this disease." (PMID 31040909, 2019). "In conclusion, our findings demonstrate for the first time that YY1 regulates transcriptional KLF4, and inhibiting YY1 expression directly affects KLF4 expression in lymphoma." (PMID 31040909, 2019). "To corroborate our results in vitro, we evaluated YY1 and KLF4 expression in patients with lymphoma." (PMID 31040909, 2019). "In addition, the expression level of YY1 in Burkitt lymphoma and DLBCL is higher than that in normal B cells and low-grade lymphoma." (PMID 37081988, 2023). "Together the results indicate that miR-7 expression plays a role in the migration capacity and chemoresistance, by regulating specific targets such as YY1 and KLF4, where these have previously been reported by our working group and others, have a role in the malignancy of lymphoma." (PMID 33194748, 2020). "This is the first report describing a correlation between KLF4 and YY1 expression in lymphoma, and this study identifies KLF4 and YY1 as potential disease markers, which could be considered biomarkers at the time of diagnosis for predicting disease behavior." (PMID 31040909, 2019). "In previous work reported by us and other authors KLF4 and YY1 independent expression does not depend on the subtype of lymphoma; however, patient samples showed a correlation as described by us and other authors." (PMID 31040909, 2019). "Furthermore, YY1 expression and KLF4 are increased in patients with lymphoma, and high expression of YY1 correlates with KLF4." (PMID 31040909, 2019). "The participation of miR-7 in the pathogenesis of lymphoma, including its role in the regulation of transcription factors that establish more aggressive patterns of lymphoma, such as KLF4 and YY1, as well as its importance in lymphoma, has not been defined." (PMID 33194748, 2020).
neuroblastoma (11 papers, 2012 to 2025). Neuroblastoma (NB) is the most common solid, extracranial childhood tumor. "In another study on neuroblastoma, YY1 was shown to facilitate aerobic glycolysis by binding to the promoter of MZF1, a zinc-finger transcription factor that upregulates glycolytic genes such as HK2 and PGK1." (PMID 41327312, 2025). "YY1 enhanced the aerobic glycolysis and proliferation of neuroblastoma cell via increasing Lactate dehydrogenase A (LDHA) expression by binding to the promoter of LDHA." (PMID 38410123, 2024). "YY1 directly bound to the promoter LDHA, and overexpression of LDHA reverses the inhibitory effect of sh-YY1 on aerobic glycolysis and proliferation of neuroblastoma cells, indicating that YY1 induces aerobic glycolysis and proliferation." (PMID 37081988, 2023). "Our results also identified the transcription factor complex YY1—which promotes neuroblastoma progression by interacting with MYCN —as regulated by ALK." (PMID 27732954, 2016). "Overexpression of YY1 in mouse neuroblastoma cells (N2a) was shown to enhance CRHR expression by increased promoter activity, suggesting that increased methylation at CpG1 of Crhr1 in LAB-CMS anxiety-exhibiting mice does not repress CRHR expression when YY1 expression is increased." (PMID 35998298, 2023). "Among them, YY1 has been reported to be directly targeted by miR-34a in neuroblastoma cells." (PMID 22829753, 2012). "ENCODE ChIP-seq screening of DEGs in KI/KI mutants revealed significant enrichment for YY1 (Yin Yang 1) binding sites (p = 2.07 × 10−12; FDR = 3.8 × 10−11; OR = 1.532), with specificity to SK-N-SH neuroblastoma cells." (PMID 41163642, 2025). "Targeting the YY1/MZF1 axis to reduce aerobic glycolysis led to a reduced tumorigenesis and aggressiveness of neuroblastoma, and thus represents a novel therapeutic target." (PMID 38893192, 2024). "The authors developed a cell-penetrating peptide (MZF1-uPEP) to disrupt the interaction between YY1 and MZF1, which consequently inhibits the transcriptional activation of genes involved in aerobic glycolysis in neuroblastoma cells." (PMID 38893192, 2024). "Transcription factors YY1 and MZF1 are thought to play a critical role in the regulation of aerobic glycolysis in neuroblastoma, and thus have been targeted in a novel therapeutic approach." (PMID 38893192, 2024). "shRNA-mediated YY1 silencing significantly reduced the activity of the TREM2 minimal promoter and TREM2 protein levels in the microglial cell line BV2 and the neuroblastoma Neuro2A." (PMID 37044212, 2023).
esophageal squamous cell carcinoma (10 papers, 2019 to 2024). Esophageal squamous cell carcinoma (ESCC) is a type of esophageal carcinoma (EC) that can affect any part of the esophagus, but is usually located in the upper or middle third. "In esophageal squamous cell carcinoma (ESCC), the Y-linked lncRNA LINC00278 encodes a Yin Yang 1 (YY1)-binding micropeptide, designated YY1BM, which inhibits the interaction between YY1 and androgen receptor (AR)." (PMID 39443468, 2024). "Yin Yang 1 (YY1) has been investigated as a transcriptional factor which enhances esophageal squamous cell carcinoma (ESCC) cell proliferation." (PMID 35778739, 2022). "YY1 was found to be overexpressed in esophageal squamous cell carcinoma (ESCC) and its expression correlated with progression and invasiveness of esophageal cancer." (PMID 31217904, 2019). "The growth of esophageal squamous cell carcinoma (ESCC) is facilitated by YY1BM, a 21 aa micropeptide encoded by LINC00278, which blocks the connection between YY1 and androgen receptor (AR), reducing eEF2K production through the AR signalling pathway." (PMID 38622617, 2024). "A Y-linked lncRNA, LINC00278 that encodes a Yin Yang 1 (YY1)-binding micropeptide (YY1BM), is down-regulated in male esophageal squamous cell carcinoma (ESCC)." (PMID 34983649, 2022). "The radiation tolerance of ESCC TE-1 cells is related to the high expression of YY1, which can inhibit the proliferation of esophageal squamous cell carcinoma cells." (PMID 34336703, 2021). "Furthermore, YY1 is overexpressed in esophageal squamous cell carcinoma (ESCC), where overexpression enhanced the progression of ESCC and correlated with a negative prognosis." (PMID 35408813, 2022).
heart failure (10 papers, 2009 to 2025). Inability of the heart to pump blood at an adequate rate to meet tissue metabolic requirements. "The expression of heart failure markers including Nppa, Nppb and Myh7 in mice treated with Yy1 was significantly reduced compared to that in DCM mice treated with EGFP control." (PMID 31705051, 2019). "Our study indicates that the miR199a-5p/Sirt1/P300/Yy1/sST2 axis might be a potent therapeutic approach for treating heart failure." (PMID 33594087, 2021). "Protein levels of PGC-1α, ERRα, Nrf1, Gabpa, and YY1 were not significantly changed in PO-induced heart failure model." (PMID 39151728, 2024). "Interestingly, both NFκB and YY1 have been involved in BACE1 regulation, and an increase in YY1 expression was observed in human heart failure." (PMID 20029627, 2009).
Hepatic steatosis (10 papers, 2013 to 2025). Steatosis is a term used to denote lipid accumulation within hepatocytes. "Notably, previous studies have linked NRF1 inactivation to the development of nonalcoholic steatohepatitis, while YY1 upregulation has been associated with fatty liver diseases, whereas E2F4 was found to promote HCC proliferation." (PMID 37627157, 2023). "Its dysregulation contributes to hallmark features of metabolic disease, including insulin resistance, hepatic steatosis, and mitochondrial dysfunction, positioning YY1 as a promising therapeutic target in metabolic disorders." (PMID 41459495, 2025). "YY1 upregulation promotes lipogenesis and hepatic steatosis by activating genes responsible for lipid biosynthesis." (PMID 41459495, 2025). "In the two other transgenic zebrafish models described by Her’s group, hepatic steatosis is induced by liver-specific overexpression of yin yang 1 (YY1) or by cannabinoid receptor 1 (CB1R)." (PMID 23720231, 2013). "Our findings suggest that YY1 may be a promising therapeutic target for fatty liver diseases and related metabolic disorders in clinic." (PMID 30285651, 2018). "In contrast, inhibition of CCAAT enhancer binding protein alpha (C/EBPα) or Yin Yang 1 (YY1) activation can improve glucose metabolism and hepatic steatosis." (PMID 39911797, 2025). "In our study, we discovered YY1 promoted transcription of TDO2 by activating H3K27ac modification in its gene region, thereby exacerbating the progression of hepatic steatosis." (PMID 39364706, 2024). "It has been reported that YY1 expression is markedly increased in patients with NAFLD and directly promotes hepatic steatosis via activation of hepatic FA synthesis." (PMID 38254634, 2023). "Our previous studies have demonstrated that Hepatitis B virus X proteins, gankyrin, Yin Yang 1 (YY1), and cannabinoid receptor 1 (CB1R) induce the development of hepatic steatosis by increasing the transcriptional activity of lipogenic gene expression in adult zebrafish." (PMID 29286302, 2017). "It has been shown that selective overexpression of YY1 results in massive triglyceride accumulation and moderate insulin resistance in mice fed with HFD, and it may be a promising target for fatty liver diseases." (PMID 34712920, 2021). "Therefore, although further investigation is required, our results demonstrate the possibility that activation of the YY1/PGC-1β axis might be crucial for liver metabolic disorder diseases, and that it might be a potential driver of HCC development from hepatic steatosis." (PMID 31695789, 2019).
laryngeal carcinoma (10 papers, 2017 to 2024). Carcinoma that arises from the laryngeal epithelium. "YY1 is a useful molecular target as a potential oncogene in head and neck squamous cell carcinomas and is especially implicated in laryngeal cancer development and progression, owing to its promoting effects on the malignant characteristics of cancer cells." (PMID 34497757, 2021). "Furthermore, high expression of YY1 mRNA and protein was associated with pro-neoplastic effects in laryngeal cancer." (PMID 33315124, 2021). "YY1 directly banded to the target promoter region of protooncogene c-Myc on laryngeal carcinoma cells and inhibited its promoter activity to promote tumor cell proliferation and migration." (PMID 35359580, 2022). "We then detected effects of YY1 knockdown on laryngeal cancer proliferation, migration, and apoptosis in the presence and absence of siMYCT1." (PMID 28485541, 2017). "YY1 promotes proliferation and migration with suppression of apoptosis via directly inhibiting MYCT1 in laryngeal cancer cells, suggesting that YY1 is a useful target as a potential oncogene in laryngeal cancer development and progression." (PMID 28485541, 2017). "Similar to MYCT1 overexpression and contrary to MYCT 1 silence, YY1 knockdown significantly decreased laryngeal cancer cell proliferation (P < 0.05) and cloning formation compared to the control (P < 0.05)." (PMID 28485541, 2017). "In the study, we confirmed that MYCT1 is a novel target of YY1 and is negatively regulated by YY1 in laryngeal cancer." (PMID 28485541, 2017). "Moreover, high expression of YY1 was detected in laryngeal cancer and head and neck squamous cell carcinoma (HNSCC), including nasopharyngeal cancer (NPC)." (PMID 35408813, 2022). "YY1 can suppress apoptosis via inhibiting MYCT1 in laryngeal cancer cells." (PMID 35408813, 2022). "Furthermore, YY1 contributes to the tumorigenesis and progression in laryngeal cancer by directly regulating MYCT1." (PMID 32943988, 2020). "We also found that high level of YY1 and low level of MYCT1 in laryngeal cancer tissues are correlated with metastasis, suggesting that both YY1 and MYCT1 genes might take part in laryngeal cancer progression." (PMID 28485541, 2017). "In addition, why YY1 is upregulated in laryngeal cancer is also required for investigation in our future study." (PMID 28485541, 2017). "Taken together, we speculate that YY1 plays a potentially oncogenic role via directly inhibiting MYCT1 expression in laryngeal cancer genesis and progression." (PMID 28485541, 2017). "In laryngeal cancer, YY1 (Yin Yang 1) binds to the promoter region of PRMT5, enhancing its transcription." (PMID 39255317, 2024). "Statistically, YY1 and MYCT1 were significantly upregulated and downregulated at transcriptional level in laryngeal cancer tissues compared to matched normal tissues, respectively (P < 0.05)." (PMID 28485541, 2017). "Therefore, we speculate that YY1 functions in laryngeal cancer probably via MYCT1." (PMID 28485541, 2017). "Real‐time RT‐PCR results indicated that high YY1 and low MYCT1 mRNA levels in laryngeal cancer tissues were observed in 19 of 30 (63.33%) and 24 of 30 (80%) cases, respectively." (PMID 28485541, 2017). "We also found that YY1 and MYCT1 are upregulated and downregulated in laryngeal cancer, respectively, implying that both genes participate in laryngeal carcinogenesis." (PMID 28485541, 2017). "Significantly higher expression of YY1 and lower expression of MYCT1 were found in laryngeal cancer tissues of patients with lymphatic metastasis than those without metastasis.YY1 directly bound to MYCT1 promoter region and inhibited its promoter activity." (PMID 28485541, 2017). "YY1 silence had similar biological functions as MYCT1 overexpression in repressiveness of proliferation and migration, and promotion of apoptosis in laryngeal cancer cells." (PMID 28485541, 2017). "However, role and mechanism of YY1 in laryngeal cancer are still unknown." (PMID 28485541, 2017).
laryngeal carcinoma (continued). "Contrary to MYCT1 knockdown, YY1 knockdown and MYCT1 overexpression significantly increased laryngeal cancer cell apoptosis compared to the control (P < 0.05)." (PMID 28485541, 2017). "YY1 promotes migration, proliferation and suppression of apoptosis in laryngeal cancer via directly inhibiting MYCT1, which can be used as target to prevent the progression of laryngeal cancer." (PMID 33344262, 2020). "YY1 promotes proliferation, migration with suppression of apoptosis via directly inhibiting MYCT1 in laryngeal cancer, suggesting that YY1 is a useful target as a potential oncogene in laryngeal cancer development and progression." (PMID 28485541, 2017). "In this study, we assessed YY1 and MYCT1 expression in laryngeal cancer tissues." (PMID 28485541, 2017). "Besides, YY1 could transcriptionally activate PRMT5 and aid in proliferation and invasion in laryngeal cancer cells." (PMID 35658060, 2022). "Taken together with the negative correlation between YY1 and MYCT1 mRNA levels, these results indicate that YY1 directly and negatively regulates MYCT1 transcription activity in laryngeal cancer." (PMID 28485541, 2017). "We also analyzed the relationships between YY1 or MYCT1 mRNA levels and metastasis in the cancer tissues from laryngeal cancer patients with or without lymphatic metastasis." (PMID 28485541, 2017). "YY1 and MYCT1 were upregulated and downregulated at transcriptional level in laryngeal cancer, respectively, which showed a negative correlation between YY1 and MYCT1 expression in laryngeal cancer." (PMID 28485541, 2017). "Real‐time RT‐PCR results also showed that YY1 and MYCT1 mRNA levels were significantly higher and lower in Hep2 cells than those in HEK293T cells (P < 0.05), respectively, further suggesting the negative correlation between YY1 and MYCT1 at transcription level in laryngeal cancer." (PMID 28485541, 2017).